RNU6-1247P (RNA, U6 small nuclear 1247, pseudogene)
Gene: Small nuclear RNA gene on chromosome 6 (151,280,515 to 151,280,612, reverse strand). Ensembl gene ENSG00000252431.
Homologues: Orthologues: chimpanzee U6 (92% identical), macaque U6 (87% identical). Paralogues in human: RNU6-16P (83% identical), RNU6-1 (82% identical), RNU6-144P (82% identical), RNU6-2 (82% identical), RNU6-3P (82% identical), RNU6-40P (82% identical), RNU6-4P (82% identical), RNU6-5P (82% identical), RNU6-6P (82% identical), RNU6-9 (82% identical), RNU6-1038P (81% identical), RNU6-12P (81% identical), and 1287 more.